EGFR (epidermal growth factor receptor)
Diseases named in the same sentence as EGFR in open-access papers (continued):
Sharing a sentence is not in itself a finding about the gene and the disease.
breast carcinoma (continued). "We found TNBC cell lines expressing higher endogenous levels of annexin A1 to be associated with overactivation of EGFR, c-Met, and pAKT pathways compared to expression levels in ER+ breast cancer cell lines." (PMID 26000884, 2015). "In conclusion, we have demonstrated for the first time that the EGFR-T790M-mutation occurs in primary human breast cancer patients." (PMID 26267891, 2015). "Due to these invariable results, our aim was to evaluate Norwegian patients for the existence of activating EGFR mutations presenting with and being treated for breast cancer in a Norwegian University Hospital." (PMID 26267891, 2015). "Co-expression of EGFR occurs in 35–65% of HER2+ breast cancer and is associated with a worse clinical prognosis than for breast cancers that don’t express EGFR." (PMID 26121470, 2015). "To the best of our knowledge, we have identified for the first time, the EGFR T790M „TKI-resistance”mutation in a subgroup of early breast cancer patients in Northern Europe." (PMID 26267891, 2015). "The germline mutations of BRCA1 and early onset of TNBC is also associated with EGFR activation in breast cancers." (PMID 25955731, 2015). "Regarding a bidirectional effect between Notch and EGFR pathway, to our knowledge, there is evidence from breast cancer cells where Notch over-expression caused EGFR up-regulation." (PMID 26497899, 2015). "Since EGFR is highly expressed in TNBC breast cancer and EGFR has been associated with metastasis and mortality of TNBC, we analyzed a potential correlation of EGFR expression in our SFBCAS TMA with FABP5 expression." (PMID 25779666, 2015). "In this study, we provide evidence for a mechanism underlying the synergy between pre-treatment with EGFR inhibitors followed by DNA-damaging chemotherapy application in breast cancer cell lines." (PMID 26036637, 2015). "High expression of EGFR is reported to be associated with poor clinical outcome in breast cancer, while its prognostic value remains debated." (PMID 25429827, 2015). "Several kinases have been implicated in maintaining STAT3 activity in breast cancer, including EGFR, JAK2, and Src." (PMID 25699542, 2015). "The biological impact of an isolated EGFR T790M mutation in BC patients should be further investigated to determine its role as a breast cancer driver and its potential as a target for therapeutic intervention." (PMID 26267891, 2015). "Patients ́characteristics: three individual Norwegian breast cancer patients with EGFR T790M mutations." (PMID 26267891, 2015). "EGFR-mutational analysis from asian groups have explored the presence of EGFR mutations in breast cancer patients, however there are limited data regarding caucasian cohorts." (PMID 26267891, 2015). "In NSCLC and breast cancer, the prevalence of EGFR mutations between Caucasian and Asian patients is different." (PMID 26046796, 2015). "Increased EGFR expression is associated with decreased sensitivity to anti-estrogens and EGFR-forced expression in ER+ breast cancer further induces hormone-independent growth." (PMID 26079946, 2015). "These investigators found that that EMT and the enrichment of breast cancer stem cells was associated with a switch from EGFR signaling to PDGFR signaling." (PMID 25253994, 2014). "Dysregulated EGFR activation is often associated with overexpression of EGFR, which has been observed in several cancer types including breast carcinomas." (PMID 25412153, 2014).
breast carcinoma (continued). "The targeting of the hormone receptor, HER2 and EGFR1 in breast cancer will be reviewed in association with suppression of the EGFR/PI3K/PTEN/Akt/mTORC1/GSK-3 pathway." (PMID 25051360, 2014). "After E2-β treatment of breast cancer cells, ER-α36 gradually dissociates from EGFR and meanwhile associates with Src and Shc." (PMID 24447535, 2014). "EGFR associates with and transactivates Axl independently of Gas6 to amplify EGFR signaling in triple negative (TN) breast cancer cells." (PMID 25344858, 2014). "The nuclear epidermal growth factor receptor (EGFR) function was also associated with (I) poor patient survival in breast cancer patients and (II) with increased local recurrence in oropharyngeal squamous cell cancer." (PMID 24647424, 2014). "The two EGFR polymorphisms were also evaluated in a combined analysis in order to investigate a possible interaction between them on the distribution of breast cancer prognostic features." (PMID 24629097, 2014). "Accumulating data suggest that there is a unique radioadaptive signaling pathway linked with induction of multidrug resistance-associated protein (MRP) and EGFR in breast cancer cells." (PMID 23990015, 2014). "Down-regulation of PTEN and oncogenic mutation of PIK3CA compounded with EGFR over expression has been correlated with poor response to trastuzumab treatment as well as a poor clinical outcome in women with HER2+ breast cancer." (PMID 25566499, 2014). "EGF “like” ligands are largely implicated in breast cancer progression, yet, most reports have only studied the expression of ligands specific to EGFR, or those specific to HER3." (PMID 25249538, 2014). "EGFR is overexpressed in 16–48% of breast cancers and its expression is associated with poor prognosis." (PMID 24575839, 2014). "The incidence of EGFR-erbB2 interaction is also implicated as a prognostic parameter for high malignancy and drug resistance of breast cancer cells, and it is also associated with the occurrence of Y845 phosphorylation." (PMID 23702846, 2013). "Endocrine treatment caused increased ligand-dependent activation of the EGFR downstream element Erk1/2, with consequential growth stimulation—which would lead breast cancer cells to develop tamoxifen resistance." (PMID 24289103, 2013). "In breast cancer, these effects were associated with increases in signaling by the epidermal growth factor receptor (EGFR) and calmodulin-dependent protein kinase II (CamKII)." (PMID 24386311, 2013). "This notion is supported by the rapid degradation of activated EGFR, loss of invasiveness and sensitivity to EGFR-targeted TKIs following down regulation of AnxA6 in invasive breast cancer cells." (PMID 24354805, 2013). "The observations that breast tumor progression associated with EGFR over-expression, phosphorylation and homo-and/or heterodimerization suggested a crucial role of EGFR in breast cancer." (PMID 24059654, 2013). "Here, we report the detailed mechanism of anti-cancer activity of DPDIM that targets the EGFR pathway to cause apoptosis in breast cancer cells and tumors." (PMID 23555785, 2013). "In male breast cancer, only expression of EGFR was significantly associated with loss of ERα and PR expression, probably due to a limited number of ERα and PR negative male breast cancer cases." (PMID 23308200, 2013). "They found high level EGFR and phosphorylated EGFR to be associated with a subset of breast cancers with HER2 enrichment, suggesting possible targets for combined therapy." (PMID 24019942, 2013). "Cross-talk between the estrogen and the EGFR/HER signalling pathways has been suggested as a potential cause of resistance to endocrine therapy in breast cancer." (PMID 23991224, 2013). "Ligands for EGFR are over-expressed in a significant proportion of breast cancers, and elevated expression of EGFR is associated with poorer clinical outcome." (PMID 24124521, 2013).
breast carcinoma (continued). "This study demonstrates that the enhanced degradation of activated EGFR in AnxA6-depleted invasive breast cancer cells underlies their sensitivity to EGFR-targeted TKIs and attenuated motility." (PMID 24354805, 2013). "One of the molecular signatures known to be associated with poor prognosis of breast cancer is the overexpression of EGFR." (PMID 23844004, 2013). "To study the effect of EBP50 expression on EGF-stimulated cell proliferation and EGFR-mediated signal transduction pathways in breast cancer cells, we combined EBP50 gain-of-function and loss-of-function studies." (PMID 22476347, 2012). "Our observation that BRCA1-associated hereditary breast cancers often showed high nuclear Kaiso, is in line with the finding that nuclear Kaiso is in general associated with high grade, basal-like and EGFR positive breast cancers." (PMID 22662240, 2012). "The expression of the EGFR has also been negatively associated with the expression of miR-30c, which was, identified as an independent predictor of outcome in advanced breast cancer; high expression of miR-30c was associated with benefit of Tamoxifen." (PMID 22623953, 2012). "Lv observed that EGFR gene mutations were rare in breast carcinomas, but EGFR gene amplification was detected in about one third of the cases in this population." (PMID 23276146, 2012). "In this study, we found that breast cancers with increased mPRα expression were associated with higher EGFR HiEx rates, a positive correlation that persisted even after adjusting the age at diagnosis and/or TNM stage." (PMID 22496908, 2012). "In their study, rare mutations in the EGFR gene in patients with breast cancer were detected, indicating that EGFR gene mutations are infrequent in this cohort of breast cancers." (PMID 23276146, 2012). "EGFR overexpression by gene amplification or by EGFR activation have been associated with several cancers, including lung and breast cancer and glioblastoma multiforme." (PMID 22662165, 2012). "In this study, EGFR mutations were presented in only two samples, indicating that EGFR mutations should not be employed in future trials with anti-EGFR therapies for breast cancer." (PMID 22132735, 2011). "The purpose of the present study was to examine 139 formalin-fixed, paraffin-embedded specimens from Chinese female patients with breast cancer, with a particular focus on the presence of EGFR gene amplification and mutations." (PMID 22132735, 2011). "This tyrosine kinase family has been heavily implicated in the mechanisms of various cancers as mutations leading to EGFR being over-expressed have often been found in cancer cases, in particular breast cancer." (PMID 22073013, 2011). "Breast cancer cell apoptosis appears to be a factor associated with cancer cell sensitivity or resistance to chemotherapy and mechanisms appear influenced by EGFR signaling." (PMID 22096483, 2011). "We observed that EGFR gene mutations were rare in breast carcinomas, but EGFR gene amplification was detected in about one third of the cases in this population." (PMID 22132735, 2011). "EGF signaling is implicated in regulating mammary gland morphogenesis and development, while aberrant EGFR activity is associated with metastasis and proliferation of breast cancer cells." (PMID 23554696, 2011). "Elevated expression of EGFR is associated with highly aggressive and metastatic cancers, including cancer of the breast." (PMID 21738726, 2011). "Increased expression of EGFR occurs frequently in human breast cancer and is associated with a poor prognosis." (PMID 22096483, 2011). "EGFR protein is expressed in 30% to 52% of triple negative breast cancers and up to 60% of the closely related basal-like breast cancers and is associated with poor prognosis." (PMID 21457545, 2011). "The aim of this study was to assess the presence of EGFR gene amplification and mutations in breast cancer and to analyze the association between the statuses of these two gene alterations." (PMID 22132735, 2011).
breast carcinoma (continued). "The aim of this study was to evaluate the frequency of EGFR gene amplification and mutations in 139 female patients with breast cancer." (PMID 22132735, 2011). "An increased level of mutation of EGFR has been detected in many human tumors, including breast cancer, which were often accompanied with a poor prognosis." (PMID 22085699, 2011). "In this study, rare mutations in the EGFR gene in patients with breast cancer were detected, indicating that EGFR gene mutations are infrequent in this cohort of breast cancers." (PMID 22132735, 2011). "Given its diagnostic and prognostic role in basal-like TN breast cancer, epidermal growth factor receptor’s therapeutic role has been assessed with drugs that antagonize its action." (PMID 21050424, 2010). "As an independent prognostic factor for breast cancer patients, EGFR is associated with a number of pathological characteristics of breast cancer." (PMID 20181250, 2010). "Among the autopsy samples of cases with primary breast cancer, we found mutations in EGFR in one liver and one lymph node metastases, and a mutation in PIK3CA in all the samples from one case, and in a liver metastasis from another." (PMID 20604919, 2010). "SRC-1 or CBP overexpression increased proliferation of human breast cancer cell lines, which correlated with increased histone acetylation and loss of nucleosome formation on the EGFR promoter." (PMID 21080969, 2010). "It has been previously shown that activating c-CBL mutation downregulates EGFR signaling and decreases cellular proliferation and migration in breast cancer cell lines." (PMID 20126411, 2010). "Increased expression of nuclear EGFR has been linked to poor clinical outcomes in patients with breast carcinoma and oropharyngeal squamous cell carcinoma." (PMID 20092659, 2010). "Considering that women with breast cancer with overexpression of EGFR are at greater risk of cancer progression, therapeutic strategies have been developed to block the activity of these receptors and to improve the response to treatment." (PMID 20169279, 2009). "A number of signaling pathways, including Her-2, EGFR and Wnt, have been implicated in the progression of breast cancer, with the Notch pathway being associated with this process more recently." (PMID 20030805, 2009). "In the clinic, increased EGFR expression has also been implicated with resistance to hormonal therapies in advanced stage breast cancers." (PMID 21892266, 2008). "An increased expression of EGFR is the hallmark of many human tumors such as breast cancer, squamous cell carcinoma of the head and neck, and prostate cancer." (PMID 18991714, 2008). "We subsequently observed that TNK2 associates with activated EGFR in breast cancer cells in a TNK2-kinase-independent manner, and furthermore that it functions to maintain EGFRs on the cell surface." (PMID 18435854, 2008). "More specifically, recent work indicates epidermal growth factor receptor (EGFR) signaling in breast cancer cells cannot compensate for loss of IGF-IR signaling." (PMID 18611244, 2008). "The human epidermal growth factor receptor (EGFR) is overexpressed in up to 20% of patients diagnosed with breast cancer and is associated with reduced survival." (PMID 18435854, 2008). "Consistent with the idea of an alternative mechanism for TNK2, we observed that TNK2 associates with activated EGFR in breast cancer cells in a TNK2-kinase-independent manner." (PMID 18435854, 2008). "In fact, since it was reportedly associated with this subtype of breast cancer in 2004, the use of EGFR in classifying basal-like tumours by immunohistochemistry has become widely accepted." (PMID 17875215, 2007). "Trastuzumab inhibits cell proliferation by driving cells into quiescence more effectively when EGFR content is low, while a high EGFR content renders breast cancer cells less susceptible to trastuzumab." (PMID 17490486, 2007).
breast carcinoma (continued). "The association of different genes with the three EGFR-associated signatures is likely reflective of the complexity of signaling in this pathway across breast cancers and suggests possible driving molecular mechanisms for each EGFR-associated profile." (PMID 17663798, 2007). "An association of EGFR with MVD in breast cancer was previously suggested in a small study of 45 patients." (PMID 17609662, 2007). "Localized amplification of the CA-SSR1 repeat, usually limited to the shorter allele, occurs frequently in breast cancers, is related to EGFR expression, and demonstrates a field effect, indicating that it is an early event during multistage pathogenesis." (PMID 17455987, 2007). "Excess activation of signaling pathways downstream of the epidermal growth factor receptor, ErbB1, has been directly linked to breast cancer development and chemotherapeutic resistance." (PMID 16984645, 2006). "Increased expression of nuclear EGFR is linked to poor clinical outcome in patients with breast carcinomas and oropharyngeal squamous cell carcinomas." (PMID 16434982, 2006). "Metaplastic breast carcinomas frequently overexpressed EGFR, which was associated with EGFR gene amplification in one-third of cases." (PMID 16280056, 2005). "Our data show that EGFR mutations occur at a significantly higher frequency in hereditary breast cancer compared to sporadic breast cancer (P=0.0079)." (PMID 15841079, 2005). "It is noteworthy that, among the 11 BRCA1/2-related breast cancers with EGFR somatic mutations, eight (72.7%) were located exclusively in the stroma." (PMID 15841079, 2005). "Because ERBB family members are strongly implicated in the aetiology of breast cancer, and because ERBB proteins and LRIG1 interact at the molecular level, we analysed the expression of EGFR/ERBB1 and ERBB2 mRNA." (PMID 16168117, 2005). "Expression of epidermal growth factor receptor (EGFr) has been shown previously to be inversely related to oestrogen receptor (ER) in patients with operable breast cancer and to be associated with a poorer prognosis." (PMID 1846551, 1991). "A promising strategy involves targeting molecular drivers like the epidermal growth factor receptor (EGFR), a member of the Epidermal growth factor receptor (ErbB) family of receptor tyrosine kinases, which is overexpressed in aggressive breast cancers and associated with poor clinical outcomes." (PMID 41552637, 2026). "Mutation of EGFR in breast cancer can range from approximately 2-11%." (PMID 40501689, 2025). "In breast cancer, it inhibits cell proliferation, migration, and invasion, with overexpression linked to improved survival outcomes and acting as an independent prognostic factor by regulating the EGFR/Akt pathway." (PMID 40650042, 2025). "Indeed, there are several recent studies investigating the efficacy of patritumab deruxtecan (HER3-Dxd) in various solid tumours such as HER2-negative breast cancer and EGFR-mutated NSCLC." (PMID 40940907, 2025). "As a predictive biomarker for EGFR inhibitors in colorectal cancer, RasGRP1 has been linked to several cancer-related processes, such as hepatocarcinoma carcinogenesis and displaying an association with improved overall survival in breast cancer." (PMID 39950162, 2025). "The combination of the target fishing approach with breast-cancer-associated genes enabled the identification of two possible targets (EGFR and PTK2B) that could serve as multi-target ligands." (PMID 40872597, 2025). "For example, trastuzumab specifically binds HER2+ breast cancer cells, whereas small-molecule EGFR-TKIs may inhibit EGFR in normal epithelia, causing skin rash or diarrhea." (PMID 41030448, 2025). "Blockade of fatty acid synthesis by resveratrol may impair the proper localization of EGFR to the cell membrane in breast cancer cells, which attenuated several signaling pathways associated with breast cancer cell proliferation and survival." (PMID 40733158, 2025).